SERPINA1 (serpin family A member 1)
Diseases named in the same sentence as SERPINA1 in open-access papers (continued):
Sharing a sentence is not in itself a finding about the gene and the disease.
cancer (continued). "We have confirmed the correlation between IL-33 and markers like SerpinA1, SerpinA3, and EphB2 for SCC and Gli1, Gli2, FOXO3A for BCC as it highlights the complex interplay of cytokines, protease inhibitors, and receptor signaling in cancer." (PMID 39839625, 2024). "We could detect upregulated genes as well (PLAU, SERPINA1, and AKT3), mainly connected to cancer development and progression and mesenchymal phenotypes, that were also responsive to EZH2 inhibition." (PMID 38672463, 2024). "The result demonstrated that SERPINA1 expression presented strong connections to B cells in 25 cancer types, CD4+ T cells in 28 cancer types, CD8+ T cells in 25 cancer types, neutrophils in 32 cancer types, macrophages in 31 cancer types, and dendritic cells (DCs) in 32 cancer types." (PMID 37511325, 2023). "Interestingly, we also observed that the expression of CDH2, SPP1, TNC, CYR61, SERPINA1, and IL6 correlated with the progression of individual cancer stages." (PMID 37887075, 2023). "Other proteins included in this component related to cancer are NUMA1, SERPINA1, and PAFAH1B3." (PMID 32525929, 2020). "Thus, cancer cells vary in the magnitude of SERPINA1 gene expression at baseline, but independently on this, produce little of endogenous AAT protein." (PMID 31487965, 2019). "Our data demonstrate that SERPINA1 gene and AAT protein not just reflect inflammatory reaction related to cancer development but play an active role in the pathogenesis of NSCLC." (PMID 31487965, 2019). "Upregulation of 48 proteins in samples of cancer patients was reported, that included several inflammation/acute phase-related proteins: A1AG1 (ORM1), A1AT (SERPINA1), AACT (SERPINA3), CO4B, CO9, HPT, ITIH4, LBP and SAA1, which upregulation was revealed also in our study." (PMID 26376850, 2015). "However, the systematical analysis of SERPINA1 in prognosis and TME regulation in cancers is rare." (PMID 37511325, 2023). "Finally, we evaluated the expression of hub genes with the development of one of the main complications of IPF patients, LUAD and LUSC, and observed that six of them (CDH2, SPP1, TNC, CYR61, SERPINA1, and IL6) were correlated with the progression of different cancer stages." (PMID 37887075, 2023). "Candidates APOA4, VDBP, A1AT/SERPINA1, and SLPI were selected for initial validation and were measured by ELISA in serum samples from 89 benign and 70 malignant ovarian cancer cases, with the latter grouped into early‐stage (FIGO I and II) and late‐stage (FIGO III and IV) cancers." (PMID 25290619, 2014). "However, no agents targeting SERPINA1 have been investigated in cancer trials thus far." (PMID 38878676, 2024). "However, a direct mechanistic link between SERPINA1 and the ubiquitination-dependent regulation of ITGB3 has not been established in any cancer type." (PMID 41467954, 2025). "SERPINA1 gene and Alpha‐1 antitrypsin protein have been recently shown to play an active role in the pathogenesis of LC such as NSCLS and not just reflect inflammatory reaction related to the cancer development." (PMID 32232956, 2020).
infection (86 papers, 2007 to 2026). The state of being infected such as from the introduction of a foreign agent such as serum, vaccine, antigenic substance or organism. "Early recognition of underlying SERPINA1 defects in children with unusual or severe infections may inform prognosis, guide management, and prompt appropriate genetic counseling and surveillance for long-term complications." (PMID 41972129, 2026). "In the current study, three SERPINs were differentially expressed following infection; SERPINA1 (α1–antitrypsin), SERPIND1 (heparin coagulation factor II) and SERPING1 (C1-inhibitor; C1INH)." (PMID 36088326, 2022). "Since ciliated and club-goblet cells are located at the apical surface, production and secretion of SERPINA1 from these cells in vivo would result in inhibition of TMPRSS2 at the natural site of infection." (PMID 35532162, 2022). "Twelve proteins were significantly increased in the binding of SERPINA1 antibody to grass carp hepatopancreas tissue before and after the infection." (PMID 36159797, 2022). "In cecum, seven upregulated genes were found in common (Gbp10, Serpina1, Ifng, Saxo1, Ighv1-59, Ighv1-63, Igkv4-79) in the infection vs. control comparisons." (PMID 36704785, 2022). "In kidney, the expression lever of SERPINA1 increased immediately after the treatment while in liver tissue it kept steady until 12 h post-infection." (PMID 31016183, 2019). "In the liver upon DHV-1 treatment, expression of du SERPINA1 increased at 12 h post-infection (h.p.i), and reached peak at 48 h.p.i, after this peak, expression of du SERPINA1 then progressively dropped." (PMID 31016183, 2019). "In the microarray used in this study, SerpinA1 (Serpin peptidase inhibitor clade A member 1) transcript was shown to increase significantly following infection." (PMID 25540075, 2014). "At 30 hpi, MEC express genes encoding different acute phase proteins, including SAA3, SERPINA1 and PTX3 and factors, such as S100A12, that contribute directly to fighting the infection." (PMID 24521038, 2014). "In this view, SERPINA1 epigenetic regulation may guarantee AAT to be active not only as inflammatory/infection-induced protease inhibitor but also as immunomodulatory and tolerogenic protein, which could be the main AAT activities during the late pregnancy." (PMID 33015055, 2020). "This epigenetic mechanism may allow SERPINA1 to be expressed independently from inflammation/infection, enabling AAT to be risen physiologically and maintained at high levels for long time period during the late pregnancy." (PMID 33015055, 2020). "However, AAT/SERPINA1 may regulate genes related to infection, inflammation, and immune response through regulation of the Slit–Robo signaling pathway." (PMID 35477570, 2022). "Combined with the results of CF2 degradation by SERPINA1 in this study, it is hypothesized that SERPINA1 may inhibit the inflammatory response induced by CF2 after GCRV infection of grass carp on the one hand, and attenuate the effect of GCRV use of CF2 to enhance infection on the other." (PMID 36159797, 2022). "HBEC ALI cultures were pretreated apically with individual recombinant SERPINA1, SERPINE1, and SERPINC1 proteins, and the infection was monitored over time." (PMID 35532162, 2022). "Moreover, the authors found that the antiviral effects of SERPINA1, SERPINE1, SERPINE2, and SERPINF1 were observed during the first steps of infection in HBEC ALI cultures, revealing reduced SARS-CoV-2 entry into target cells." (PMID 38601158, 2024). "DK212 infection substantially repressed CD36, THBS1, and SERPINA1 expression, which might prevent the maturation of immature dendritic cells." (PMID 36059479, 2022). "Finally, SerpinA1 regulates immune responses by controlling inflammation, therefore reducing target cells during exposure to HIV or once the infection has been established." (PMID 26091527, 2015).
infection (continued). "Furthermore, we assessed whether these differences could help us predict how liver cells without the Serpina1 gene react to inflammatory stimuli (infection, trauma, etc.)and what can be the expected putative systemic consequences." (PMID 36142337, 2022).
genetic disorder (62 papers, 2008 to 2026). "Alpha-1-antitrypsin (AAT) deficiency (AATD) is a genetic disorder caused by mutations of the SERPINA1 gene." (PMID 39987184, 2025). "AAT deficiency is a genetic disorder that results from a homozygous “Z” mutation in the SERPINA1 gene which encodes AAT." (PMID 37762367, 2023). "AATD is a rare genetic disease due to mutations of the SERPINA1 gene that produce low levels or defective AAT in the blood." (PMID 36553867, 2022). "SERPINA1 deficiency results in a genetic disorder that damages the liver and lung as a result of uncontrolled neutrophil elastase and non‐functional SERPINA1 in the liver." (PMID 33336526, 2021). "AATD is an autosomal, codominant, genetic disorder that is characterized by low circulating levels of AAT as a result of a mutation of the SERPINA1 gene." (PMID 29618937, 2018). "Alpha-1-antitrypsin (AAT) deficiency is a genetic disorder that produces inactive/defective AAT due to mutations in the SERPINA1 gene encoding AAT." (PMID 30009048, 2018). "Alpha‐1 antitrypsin (AAT) deficiency is a genetic disorder characterized by impaired production of the AAT, which is explained by mutations in the SERPINA1 gene, which codes for AAT." (PMID 40833357, 2026). "Alpha1‐antitrypsin (AAT) deficiency is one of the most common genetic diseases caused by mutations in the serpin family A1 (SERPINA1) gene, which encodes the AAT protein." (PMID 41503026, 2026). "Alpha‐1‐antitrypsin deficiency (AATD) is a rare genetic disorder caused by mutations in the SERPINA1 gene, which encodes alpha‐1‐antitrypsin (AAT), a critical protein involved in protecting lung tissue from damage caused by neutrophil elastase." (PMID 39777754, 2025). "Alpha-1 antitrypsin (AAT) encoded by SERPINA1 is an acute-phase inflammation marker, and AAT deficiency (AATD) is known as one of the common genetic disorders in European populations." (PMID 26174136, 2015). "A1ATD is one of the most frequently inherited genetic disorders within the Caucasian populations, with an incidence of 1/ 1500—4500 people and caused by autosomal recessive pathogenic mutations in the SERPINA1 gene, encoding for A1AT." (PMID 35505316, 2022).
respiratory diseases (14 papers, 2008 to 2026). "Various literature studies are available for the correlation of the SERPINA1 allelic variations at rs28929474 and rs17580 with respiratory diseases, specifically COPD." (PMID 36320441, 2022). "However, the recent implementation of serum AAT dosage and SERPINA-1 genetic testing in patients affected by several respiratory diseases or unexplained dyspnea has increased the detection not only of the already known deficient variants, but also of the new rare PI* alleles." (PMID 38398397, 2024).
cardiovascular disease (13 papers, 2012 to 2025). "Furthermore, the gene SerpinA1 or α1-antitrypsin was downregulated under CR and is a marker for inflammatory processes usually associated with atherogenesis and cardiovascular diseases." (PMID 28575190, 2018).
metabolic disease (8 papers, 2012 to 2025). A congenital disorder (due to inherited enzyme abnormality) or acquired (due to failure of a metabolically important organ) disorder resulting from an abnormal metabolic process. "Alpha‐1 antitrypsin deficiency (A1ATD) is an inherited metabolic disorder caused by a mutation (ZZ) in the SERPINA1 gene." (PMID 40248356, 2025).
neurological disorders (5 papers, 2020 to 2022). "Another study representing the first transcriptome sequencing study proposed the association of seven genes (CTSS, SERPINA1, NPTX1, PTX3, CHI3L1, SERPINA3, and MX1) as “the missing link” to explain the correlation between HHV-6A infection and neurological diseases." (PMID 35683449, 2022). "SERPINA1 may thus warrant investigation as a target for other neurological disorders as well." (PMID 33871358, 2021). "The network “Cellular assembly and organization, Neurological disease, Organismal development” was predicted with a high score for EAE-16d in IPA and involved the acute phase proteins HEMO (hemopexin, gene: HPX), A1AT (alpha-1-antitrypsin 1–1, gene: SERPINA1) and CO3 (complement 3, gene: C3)." (PMID 33785790, 2021).
digestive system tumors (1 paper, 2023). "Then, we focused on the relationships between SERPINA1 expression and immune cells in seven digestive system tumors using the R package MCPcounter." (PMID 37511325, 2023).
SERPINA1 also shares sentences with these, for which no sentence is quoted: hemochromatosis (16 papers); panniculitis (16); lupus (14); non-small cell lung carcinoma (13); Protein-losing enteropathy (13); Alagille syndrome (12); bacterial infection (12); Hepatitis (12); renal diseases (12); vasculitis (12); autoimmune hepatitis (11); inflammation (10); nephrotic syndrome (10); type 2 diabetes (10); biliary atresia (9); chronic kidney disease (9); adenocarcinoma (8); depression (8); hereditary hemochromatosis (8); idiopathic pulmonary fibrosis (8); ischemic stroke (8); melanoma (8); primary biliary cholangitis (8); primary sclerosing cholangitis (8); enteropathy (7); hepatitis B (7); interstitial lung disease (7); non-alcoholic steatohepatitis (7); nonalcoholic fatty liver disease (7); viral hepatitis (7).
A further 396 diseases each share a sentence with SERPINA1 in 6 papers or fewer.